BCAR4 (breast cancer anti-estrogen resistance 4)
Gene: Long non-coding RNA gene on chromosome 16 (11,798,461 to 11,828,977, reverse strand). Ensembl gene ENSG00000262117.
Diseases named in the same sentence as BCAR4 in open-access papers:
BCAR4 is named in the same sentence as 35 diseases in open-access papers, as found by Europe PMC text mining. Sharing a sentence is not in itself a finding about the gene and the disease. The quoted sentences say what the papers report.
breast cancer (75 papers, 2007 to 2025). A primary or metastatic malignant neoplasm involving the breast. "A meta-analysis in breast cancer confirmed an association between the breast cancer resistance 4 (BCAR4) gene and resistance to ET, with BCAR4 expression being clinically significant in both luminal A and B subtypes." (PMID 40244377, 2025). "For example, the distant metastasis-free survival, overall survival, and progression-free survival of breast cancer patients are strongly associated with high expression of BCAR4, LUCAT1, and TINCR." (PMID 38233788, 2024). "BCAR4 overexpression, which was associated with tamoxifen resistance and poor outcomes, sensitized breast cancer cells to lapatinib." (PMID 36081848, 2022). "Up-regulation of BCAR4 (the CA153 susceptibility gene) in the human breast cancer ZR-75-1 cell line promotes the phosphorylation of ERBB2 and ERBB3, enhances the estrogen-dependent effect of tumor cells, and stimulates the proliferation of tumor cells." (PMID 34630106, 2021). "Recently, fusion variants of the breast cancer anti-oestrogen-resistance 4 (BCAR4) gene were recurrently discovered in lung adenocarcinoma from the genome-wide studies." (PMID 33204025, 2021). "Breast cancer anti-estrogen resistance 4 (BCAR4) is closely associated with colorectal cancer (CRC) initiation and propagation." (PMID 30962766, 2019). "For example, the most dysregulated lncRNA gene, BCAR4, has been found to be overexpressed in breast tumor tissue in previous studies and was associated with poor survival of breast cancer patients." (PMID 30026672, 2018). "BCAR4 was originally found associated with tamoxifen resistance in breast cancer, in which it likely mediated the function through activating GLI2 signaling." (PMID 30513511, 2018). "Markedly elevated BCAR4 (Breast Cancer Anti-Estrogen Resistance 4, BCAR4) is associated with lung metastasis by activation of transcription of GLI2-dependent gene." (PMID 28103585, 2017). "Of the known lncRNAs associated with breast cancer, BCAR4 is most noteworthy for its role in endocrine resistance (see Long noncoding RNAs and tamoxifen resistance)." (PMID 25849966, 2015). "BCAR4 encodes a functional protein, which drives proliferation of endocrine-resistant breast cancer cells." (PMID 26317614, 2015). "In primary breast cancers, BCAR4 expression was comparatively rare (10%), but associated with enhanced proliferation." (PMID 26317614, 2015). "Importantly, BCAR4 overexpression, which has been linked to tamoxifen resistance and poor outcomes, at the same time made breast cancer cells more sensitive to lapatinib." (PMID 38919532, 2024). "To address the question whether BCAR4 is associated with clinical tamoxifen resistance, we studied 280 ERα-positive primary breast cancer specimens from patients with advanced disease." (PMID 20859285, 2010). "Overexpression of Breast Cancer Anti-Estrogen Resistance 4 (BCAR4), associated with rapid disease progression and poor prognosis, has also been proposed as a signature of tamoxifen resistance in BC." (PMID 32967267, 2020). "The lncRNA breast cancer anti-estrogen resistance 4 (BCAR4) is associated with advanced BC and metastasis." (PMID 32188472, 2020). "In 2006, it was first discovered that lncRNAs, specifically the ectopic expression of BCAR4 (breast cancer antiestrogen resistance 4), can significantly affect the degree of tamoxifen resistance in ZR-75-1 human breast cancer cells." (PMID 38668383, 2024). "The lncRNA breast cancer anti-estrogen resistance 4 (BCAR4) is required for YAP-dependent glycolysis." (PMID 38408962, 2024). "Breast cancer anti-estrogen receptor 4 (BCAR4) is a lncRNA that has been initially identified as anti-estrogen resistant in breast cancer cells." (PMID 36605618, 2023). "For instance, BCAR4-targeted ASOs were found to be able to effectively inhibit metastasis in breast cancer mouse models." (PMID 37415734, 2023).
breast cancer (continued). "In breast cancer, the lncRNA BCAR4 was identified as a downstream target of YAP that controls cancer development, by reprogramming glucose metabolism through the transcription of two glycolysis activators, Hexokinase 2 (HK2) and PFKFB3." (PMID 37689702, 2023). "BCAR4 was originally identified from the genes responsible for tamoxifen resistance in breast cancer cells as named as a breast cancer anti-estrogen resistance 4 gene." (PMID 36081848, 2022). "BCAR4, as the gene name suggests, was identified as an antiestrogen resistance gene in breast cancer." (PMID 36081848, 2022). "BCAR4 has been shown to exert an oncogenic role in breast cancer inducing endocrine resistance in these cells." (PMID 36119500, 2022). "BCAR4 (Breast cancer anti-oestrogen resistance 4) is a nuclear lncRNA with oncogenic function that regulates glycolysis." (PMID 36182907, 2022). "BCAR4 has been investigated in various cancers, and its oncogenic role has been reported in breast cancer, colorectal cancer, and cervical cancer." (PMID 36081848, 2022). "The overexpression of YAP (p = 0.0166) and BCAR4 (p = 0.0173) correlates with a poor recurrence-free survival (RFS) for breast cancer patients." (PMID 33652661, 2021). "A study showed that BCAR4 and YAP expressions were positively correlated in breast cancer and closely associated with unfavourable recurrence‐free survival." (PMID 32779318, 2020). "Many studies have indicated that several lncRNAs, such as HOTAIR, linc-ROR, and BCAR4, are upregulated and they promote breast cancer invasion and metastasis." (PMID 32929060, 2020). "Another lincRNA, breast cancer anti-estrogen resistance 4 (BCAR4), was identified in a functional screening of genes regulating the tamoxifen resistance of an ER-positive breast cancer cell line, ZR-75-1." (PMID 32486413, 2020). "The following depicts the role of lncRNA, BCAR4, in the metastasis of breast cancer via chemokine-induced binding of BCAR4 to two transcription factors having extended regulatory consequences." (PMID 32490292, 2020). "BCAR4 has been identified as a TNBC-upregulated lncRNA that is essential for breast cancer metastasis." (PMID 33123488, 2020). "Breast Cancer Anti-estrogen Resistance 4 (BCAR4) was previously characterised in bovine species as a gene preferentially expressed in oocytes, whose inhibition is detrimental to in vitro embryo development." (PMID 32193429, 2020). "LncRNA breast cancer anti-estrogen resistance 4 (BCAR4) was first identified as playing an oncogenic role in breast cancer." (PMID 32244924, 2020). "Aberrant expression of BCAR4 (breast cancer anti-estrogen resistance 4) is mainly involved in acquiring BC tamoxifen resistance in an independent manner of estrogen receptor I (ESRI)." (PMID 32397382, 2020). "LncRNA BCAR4 was first identified as anti-estrogens-resistant in breast cancer cells, and it was located on chromosome 16p13.13." (PMID 31124974, 2019). "More advanced studies revealed that long non-coding RNA breast cancer anti-estrogen resistance 4 (BCAR4) facilitated colon cancer progression through activating wnt/β-catenin pathway." (PMID 30962766, 2019). "Previously, lncRNA BCAR4 was considered as an oncogene and was reported to play a pivotal role in metastasis and tamoxifen-resistance of breast cancer." (PMID 31762809, 2019). "Since long non-coding RNA breast cancer anti-estrogen resistance 4 (lncRNA BCAR4) is dysregulated in various types of cancers, we conducted a meta-analysis to determine its prognostic value in cancer." (PMID 31124974, 2019). "In breast cancer cells, long non-coding RNA breast cancer anti-estrogen resistance 4 (BCAR4) coordinates with the GLI2-dependent Hedgehog signaling to mediate YAP-induced glycolysis, and forms a YAP-BCAR4/GLI2-glycolysis axis." (PMID 30176928, 2018). "Breast-Cancer Anti-Estrogen Resistance 4 (BCAR4) is a lncRNA that plays a pivotal role in the tamoxifen-resistance of breast cancer." (PMID 30513511, 2018).
breast cancer (continued). "BCAR4 was originally identified as a breast cancer oncogene in a functional screen for genes involved in tamoxifen resistance." (PMID 29732012, 2018). "BCAR4 expression indicates aggressiveness and poor prognosis of human breast cancer, osteosarcoma, non-small cell lung cancer, and cervical carcinoma." (PMID 30513511, 2018). "BCAR4 has been shown binding to the promoter of GLI2 to activate GLI2 signaling pathways in breast cancer cells, and in osteosarcoma cells." (PMID 30513511, 2018). "Recently, it was reported that BCAR4 expression negatively correlates with breast cancer disease progression." (PMID 29299178, 2017). "Among those different genes, breast cancer anti-estrogen resistance 4 (BCAR4) was found to be closely related to tamoxifen resistance." (PMID 27732939, 2017). "Previously, this same group reported that over-expression of BCAR4 gives rise to aggressive phenotypes and anchorage-independent growth in breast cancer cell lines." (PMID 29299178, 2017). "Due to the important role of BCAR4 in CCL21-induced hypophosphorylation of RNA Pol II Ser5, locked nuclear acid (LNA) has been used to target BCAR4 and suppress metastasis of breast cancer in mouse models." (PMID 27732939, 2017). "The authors found that out of 280 breast cancer patients, 81 patients (29%) showed high expression levels of the BCAR4 gene." (PMID 29299178, 2017). "BCAR4 is a strong oncogene that transforms breast cancer cells into an estrogen-independent, antiestrogen-resistant state." (PMID 27713133, 2017). "Recently, BCAR4 (Breast Cancer Anti-Estrogen Resistance 4) that was categorized as lncRNAs was identified as an oncogene in breast cancer." (PMID 29190958, 2017). "Recently, lncRNAs such as lncRNA-ATB, GAS5, HOTAIR, CCAT2, H19, BCAR4, UCA1, LncRNA-ROR and LncRNA-ARA have been implicated in resistance to chemotherapy in breast cancer patients." (PMID 29299178, 2017). "Increased BCAR4 level was correlated with progressive mammary cancer, and targeting BCAR4 based on knockout of specific gene intensively suppressed breast cancer spread in an animal model." (PMID 27686732, 2016). "For example, inhibiting lncRNA BCAR4 with locked nucleic acid (LNA)-based antisense oligonucleotides suppressed the metastasis of breast cancer." (PMID 26349457, 2016). "Using that approach, we have previously identified Breast Cancer Anti-Estrogen Resistance 4 (BCAR4) as a mediator of cell proliferation and tamoxifen-resistance." (PMID 26317614, 2015). "BCAR4 mRNA expression was evaluated by (q)RT-PCR in a panel of human normal tissues, primary breast cancers and cell lines." (PMID 26317614, 2015). "The lncRNA BCAR4 was discovered in a functional screen of ZR-75-1 breast cancer cells to identify mechanisms of anti-estrogen resistance." (PMID 25849966, 2015). "BCAR4 protein was detected in breast cancer cells with ectopic (ZR-75-1-BCAR4) and endogenous (IPH-926, MDA-MB-453) BCAR4 mRNA expression." (PMID 26317614, 2015). "We have previously isolated Breast Cancer Anti-estrogen Resistance 4 (BCAR4), a gene that can override tamoxifen-induced growth suppression in vitro." (PMID 26317614, 2015). "According to the lncRNADisease Database, there are 16 lncRNAs known to play a role in breast cancer including H19, growth arrest-specific 5 (GAS5), homeobox antisense intergenic RNA (HOTAIR), and breast cancer anti-estrogen resistance 4 (BCAR4)." (PMID 25849966, 2015). "This allowed for the analysis of clinical benefit, PFS and post-relapse survival in advanced breast cancer patients in relation to BCAR4 mRNA levels in the primary tumour." (PMID 20859285, 2010). "In the tamoxifen-sensitive ZR-75-1 human breast cancer cell line, forced expression of BCAR4 induced tamoxifen-resistant proliferation." (PMID 20859285, 2010). "Breast cancer anti-oestrogen resistance 4 (BCAR4) was identified in a search for genes involved in anti-oestrogen resistance in breast cancer." (PMID 20859285, 2010).
breast cancer (continued). "In conclusion, high levels of BCAR4 mRNA predict resistance to endocrine therapy and poor outcome in ERα-positive breast cancer." (PMID 20859285, 2010). "Additionally, the breast cancer anti-estrogen resistance 4 (BCAR4) lncRNA has been identified as an oncogene in breast cancer and is also found to be upregulated in colon cancer tissues." (PMID 40362520, 2025). "Besides BCAR4, other lncRNAs stimulates glycolysis in breast cancer cells enhancing the transcription of specific enzymes or supporting enzyme catalytic activity, for example lncRNA YIYA that promote activation of the PFKFB3 enzyme." (PMID 36182907, 2022). "Additionally, high expression of BCAR4 sensitized breast cancer cells to the combination of lapatinib and tamoxifen." (PMID 36081848, 2022). "Clinically, BCAR4 and YAP expression are positively correlated in breast cancer and high expression of both BCAR4 and YAP is associated with poor survival of patients with breast cancer." (PMID 36182907, 2022). "Another study proved that upregulated lncRNA breast cancer anti-estrogen resistance 4 (BCAR4) in triple negative breast cancer is transcriptionally targeted by Yes-associated protein (YAP) and it is required for YAP-promoted glycolysis through GLI2-dependent Hedgehog signaling." (PMID 33652661, 2021). "Although this activity of BCAR4 contributes to breast cancer metastasis, whether this mechanism is involved in the resistance to tamoxifen and ICI182,780 remains unknown." (PMID 32486413, 2020). "In ER+ breast cancer, BCAR4 promoted tumor proliferation and endocrine therapy resistance." (PMID 32393270, 2020). "We further identified several novel pan-cancer splice variants (chr16:11851406 with chr16:11820297, chr16:11821755 and chr16:11828391, each present across up to eight different cancers) in RSL1D1 and its neighboring BCAR4, a long non-coding RNA known to promote breast cancer progression." (PMID 34316681, 2020). "The lncRNA BCAR4 (breast cancer anti-estrogen resistance 4), originally identified in breast cancer, has been described to directly interact with and stabilize β-Catenin protein, which enhances the expression of Wnt target genes, such as MYC and CCND1, by preventing β-Catenin degradation." (PMID 33352769, 2020). "Furthermore, high expression of both BCAR4 and YAP is associated with poor survival of patients with breast cancer, suggesting a critical role for the YAP-BCAR4-glycolysis axis in this disease." (PMID 33123488, 2020). "In addition, BCAR4 induction in estrogen dependent breast cancer cell line, ZR-75-1, led to an increase resistance to tamoxifen therapy." (PMID 35582574, 2019). "Breast cancer anti-estrogen resistance 4 (BCAR4) gene produces a spliced lncRNA that has been firstly identified to be inversely associated with the development of resistance to anti-estrogens in breast cancer cells and poor disease-free survival (DFS) for recurrent breast cancer." (PMID 31762809, 2019). "Additionally, ectopic expression of BCAR4 in the breast cancer cell lines MCF7 and ZR-75-1 resulted in increased cellular proliferation in estrogen free media." (PMID 29732012, 2018). "BCAR4 may function as a suitable target for treating antiestrogen resistance in breast cancer by harnessing this tissue specific restricted expression pattern displayed by it." (PMID 29732012, 2018). "BCAR4 can override tamoxifen-induced proliferation suppression in breast cancer." (PMID 29190958, 2017). "Here, we show high level of expression and function of BCAR4 in human breast cancer." (PMID 26317614, 2015). "Together, these data firmly establish the role of BCAR4 in breast cancer biology." (PMID 26317614, 2015). "Besides, BCAR4 could wire up the Hippo pathway effector- Yes-associated protein (YAP) and Hedgehog (Hh) signaling to reprogramme glucose metabolism in breast cancer." (PMID 31762809, 2019).
breast cancer (continued). "However, if a method of RNA interference is developed to diminish levels of BCAR4 in breast cancer patients, this could also be a rational therapy." (PMID 25849966, 2015). "For example, BCAR4 expression was driven in human ZR-75–1 and MCF7 breast cancer cells, which resulted in cell proliferation." (PMID 38166659, 2024). "The expression levels of BCAR4 and YAP were positively correlated in tissue samples from breast cancer patients, where high expression of BCAR4 and YAP was associated with poor survival prognosis." (PMID 38408962, 2024). "In breast cancer, multiple lncRNAs played an important role in the regulation of TRAIL, like HOTAIR, NEAT1, BCAR4 and DSCAM-AS1." (PMID 34282054, 2021). "Notably, lncRNA breast cancer antiestrogen resistance 4 (BCAR4) has been proven to regulate the proliferation, stemness, and metastasis of various types of cancer, including breast cancer (BC), colorectal cancer (CC) and non-small cell lung cancer (NSCLC)." (PMID 33602031, 2021). "Meanwhile, it has been previously observed that many lncRNAs participate in the occurrence and progression of breast cancer, including LncRNA-ATB, DSCAM-AS1, and LncRNA BCAR4." (PMID 32849791, 2020). "Co-expression of BCAR4 and low level of ERBB2 occurs frequently and indicate a worse PFS outcome for breast cancer patients undergoing tamoxifen resistance." (PMID 31762809, 2019). "Breast cancer antiestrogen resistance 4 (BCAR4) is related to tamoxifen resistance and could also sensitize BC cells to lapatinib." (PMID 29983835, 2018). "It should be also noted that our ERα-dependent lncRNA set does not contain most of the lncRNAs that were previously studied in breast cancer, such as HOTAIR, CCAT2, UCA1, MALAT1, BCAR4, EGOT, SPRY4-IT1 and others." (PMID 26621851, 2016). "Relative high BCAR4 mRNA expression was identified in IPH-926, a cell line derived from an endocrine-resistant lobular breast cancer." (PMID 26317614, 2015). "Furthermore, a series of lncRNAs have been elucidated to serve as important prognostic hallmarks in numerous tumors, for instance, MALAT1 in breast cancer and digestive system cancer, XIST in various solid tumors, BCAR4 and SNHG16 in diverse human neoplasms." (PMID 33639865, 2021). "Some lncRNAs affect chromatin organization by binding to proteins, they operate biological functions without directly interacting with chromatin such as BCAR4 in breast cancers." (PMID 32673448, 2020). "Breast cancer anti-estrogen resistance 4 promotes the CRC cells stemness through targeting to miR-665/STAT3 signaling and identification of the BCAR4 in CRC stem cells provides a new insight into CRC diagnosis, treatment, prognosis and next-step translational investigations." (PMID 30962766, 2019). "Previous studies have found that BCAR4 contributes to antiestrogen resistance and promotes breast cancer proliferation and metastasis through regulating noncanonical Hedgehog/GLI2 pathway." (PMID 30513511, 2018). "BCAR4 (breast cancer antiestrogen resistance 4), as a type of LncRNA connected with resistance to tamoxifen which is an endocrine drug, may be detected in 10–27% BC samples." (PMID 30459529, 2018). "BCAR4 expression is upregulated and acts as an oncogenic noncoding RNA in breast cancer, non-small cell lung cancer and so on." (PMID 29190958, 2017). "BCAR4 (Breast Cancer Anti-Estrogen Resistance 4) is a long noncoding RNA that was identified as an oncogene in breast cancer." (PMID 29190958, 2017). "BCAR4 could induce the activation of GLI’s target genes and promotes breast cancer metastasis, especially triple-negative breast cancer." (PMID 26349457, 2016). "Moderate BCAR4 expression was evident in MDA-MB-134 and MDA-MB-453 breast cancer cells." (PMID 26317614, 2015). "In the second group, including only patients with lymph node-negative cancer, ERα-positive breast cancer, we investigated the prognostic value of BCAR4 mRNA levels." (PMID 20859285, 2010).